PTH (parathyroid hormone)
Diseases named in the same sentence as PTH in open-access papers (continued):
Sharing a sentence is not in itself a finding about the gene and the disease.
secondary hyperparathyroidism (continued). "The group confirmed the negative correlation between 25-hydroxyvitamin D and PTH: more than third (35.3%) of the case series had secondary hyperparathyroidism, with significant higher prevalence among participants in the lowest 25-hydroxyvitamin D quartile compared to those in the highest quartile." (PMID 34564834, 2022). "This study indicates that elevated PTH in dialysis patients could be not solely a consequence of secondary hyperparathyroidism, but also partly of impaired liver function and consequently impaired metabolic clearance." (PMID 33660959, 2021). "In detail, serum leptin was negatively correlated to PTH in three clinical studies including 46, 73, and 161 hemodialysis patients, respectively, confirming the negative impact of secondary hyperparathyroidism on leptin secretion remarked in experimental studies." (PMID 34422722, 2021). "When divided into two groups, the median concentrations of preptin were markedly elevated in patients with PTH > 200 pg/mL—1439.5 ng/L ± 2186.75 (median: 695.5) respectively—as compared to the patients without secondary hyperparathyroidism—665 ng/L ± 658 (median: 452 ng/L), respectively (p < 0.05)." (PMID 33921361, 2021). "In patients with moderate-to-severe CKD (stages 2–5), obesity worsens secondary hyperparathyroidism and, regardless of CKD, obesity is associated with hyperparathyroidism, increased PTH levels, insulin resistance, and low-grade inflammation but not with WAT browning." (PMID 32751307, 2020). "However, as the measurement of serum parathyroid hormone (PTH) was not included in the study, we were unable to determine whether the associations between serum 25(OH)D concentration with adiposity and lipid profile were caused by secondary hyperparathyroidism." (PMID 32326217, 2020). "Concerning the possible adverse impact on bone health in absence of PTH, our present study herein was mainly focused on the bone mineral status in secondary hyperparathyroidism and the effect of total parathyroidectomy without autotransplantation on bone density changes." (PMID 29907149, 2018). "Although PTH levels were not available, the proportion of patients in our cohorts with eGFR below that threshold was considerably low (4% in RS-I and 2% in RS-II) suggesting that secondary hyperparathyroidism is unlikely to explain our findings." (PMID 29766437, 2018). "The lack of differences in these results including ours may likely be due to dialysis vintage and that modest reductions in phosphate do not alter PTH levels given the progressive nature of moderate and severe secondary hyperparathyroidism." (PMID 27252880, 2016). "Although the doses and duration of the therapies were similar in all of the patients in our study, high serum levels in the patients with elevated serum PTH and FGF-23 levels could be insufficient in suppression of PTH secretion and resulted in the development of secondary hyperparathyroidism." (PMID 25295189, 2014). "Secondary hyperparathyroidism (SHPT) is one of the most common abnormalities of mineral metabolism in patients with chronic kidney disease (CKD), and is characterized by hyperplasia of the parathyroid glands and increased plasma levels of parathyroid hormone (PTH)." (PMID 23133549, 2012). "One reason for the absence of any increase in PTH (secondary hyperparathyroidism) during winter may be the presence of sufficient levels of 25OHD metabolites throughout the year may." (PMID 21731765, 2011). "However, it is possible that at least part of the subjects had secondary hyperparathyroidism, as there was a negative correlation between serum PTH and 25(OH)D levels." (PMID 22190928, 2011). "CKD-related disturbances of the calcium-phosphate-PTH axis (CKD-MBD) may represent an additional but uncommon secondary context, with the strongest support coming from case-based observations, especially in severe or uncontrolled secondary hyperparathyroidism and phosphate retention." (PMID 41531582, 2025).
secondary hyperparathyroidism (continued). "Besides, we did not have data on serum 25(OH)D or PTH, which are major determinants of calcium-phosphate homeostasis and bone metabolism; therefore, we were unable to adjust for vitamin D status or secondary hyperparathyroidism, and residual confounding by these factors cannot be excluded." (PMID 41550870, 2025). "However, at that time, there was likely a contributing component of secondary hyperparathyroidism, evident from the low urinary calcium and severely elevated PTH levels, which could not be explained by FHH." (PMID 41210046, 2025). "Secondary hyperparathyroidism (SHPT), commonly develops during stages 3 and 4 of CKD, may lead to cardiovascular calcifications by other mechanisms including an impaired effect of parathyroid hormone (PTH), and a decreased calcium-sensing receptor (CaR) expression on cardiovascular structures." (PMID 39165274, 2024). "There is certain evidence that treatments designed to control parathyroid hormone (PTH), Ca and P levels in patients with advanced CKD such as calcimimetics and phosphate binders may attenuate calcification progression in HD patients with secondary hyperparathyroidism." (PMID 29350348, 2018). "In addition, two patients in the lithium group and one patient in the non-lithium group were excluded due to suspected secondary hyperparathyroidism (parathyroid hormone concentrations above the reference range in conjunction with 25-hydroxycholecalciferol levels below the reference range)." (PMID 25505674, 2013). "Although the observed differences between the two PTH assays were higher in both the pre-dialysis and dialysis CKD groups, there was no change in interpretation of secondary hyperparathyroidism with either assay." (PMID 40937300, 2025). "Alternatively, the persistence after a calcium load test of normal ionized calcium and PTH serum concentration rules out PHPT and drives one to a diagnosis of secondary hyperparathyroidism related to a normal/low ionized calcium serum level in a fasting state." (PMID 38497124, 2024). "In addition, because we did not measure serum calcium and parathyroid hormone, we could not determine whether the association of 25(OH)D with SUA was partly mediated by calcium or secondary hyperparathyroidism, although individuals with self-reported thyroid or parathyroid disease were excluded." (PMID 23585876, 2013). "There was only one exception: PTH in MACS-positive-BT versus UT was higher, but with intra-normal variations, noting that 25-hydroxyvitamin D and serum calcium levels were not different in order to suspect a component of secondary hyperparathyroidism." (PMID 41157311, 2025). "In fact, secondary hyperparathyroidism and VDD are consequences of obesity, and if not coupled with an increase in PTH, diminished 25(OH)D3 levels may not reflect bona fide VDD." (PMID 36556486, 2022). "We report a first case of a hemodialysis (HD) patient with secondary hyperparathyroidism (SHPT), in whom cinacalcet, but not etelcalcetide, could reduce serum intact PTH (i-PTH) levels." (PMID 34787825, 2022). "Nearly half (46%) of women with OP had compensatory secondary hyperparathyroidism, but a significant adverse BMD effect in ascending PTH tertials, could not be demonstrated (p = 0.720)." (PMID 30939140, 2019). "We did not measure PTH levels in this study to assess the relationship between PTH and serum blood sugar level but 25-OHD level in diabetics in our study was less than 20 ng/mL in the majority of patients, thus most of them might have secondary hyperparathyroidism." (PMID 24251044, 2013).
hyperparathyroidism (662 papers, 2005 to 2026). Hyperfunction of the parathyroid glands resulting in the overproduction of parathyroid hormone. "PTH levels are usually evaluated in the presence of pathologies associated with an altered calcium metabolism, such as renal failure, osteoporosis, and hyperparathyroidism or hypoparathyroidism." (PMID 40290309, 2025). "Hyperparathyroidism is an autoimmune disease caused by the abnormal secretion of the parathyroid hormone." (PMID 40075889, 2025). "Long-standing hyperparathyroidism, increased preoperative plasma calcium, PTH, and bone diseases are acknowledged risk factors for developing HBS." (PMID 40026929, 2025). "Hyperparathyroidism (HPT) is an endocrine disorder in which parathyroid glands secrete elevated levels of parathyroid hormone (PTH), causing disruption in calcium metabolism." (PMID 39958142, 2025). "Hyperparathyroidism (HPT) is characterized by excessive secretion of parathyroid hormone (PTH) and is a cause-and-effect disorder of calcium (Ca), phosphorus (P), and vitamin D metabolism." (PMID 41597072, 2025). "Hyperparathyroidism is characterized by continuous exposure to excessive endogenous PTH, causing increased bone turnover in favor of bone resorption." (PMID 40177730, 2025). "Normocalcemic hyperparathyroidism presents a unique diagnostic challenge due to its normal serum calcium levels despite elevated parathyroid hormone levels." (PMID 39820817, 2025). "In summary, this study concludes that advanced age, prolonged dialysis duration, concomitant diabetes, hypertension, hyperparathyroidism, and elevated levels of PTH and hs-CRP are significant risk factors for CAC in patients with ESRD." (PMID 40314886, 2025). "Hyperparathyroidism (HPT) is caused by an increase in parathyroid hormone (PTH) production by one or more parathyroid glands." (PMID 39958142, 2025). "In Korea, one study on 46 children have found a 26% prevalence of hyperparathyroidism; key risk factors identified include prolonged dialysis and elevated PTH levels before and after KT." (PMID 40451790, 2025). "Total PTx requires greater post-operative resources but is associated with lower PTH values at 12-months, whereas subtotal PTx is associated with a lower pill burden but increased hyperparathyroidism recurrence." (PMID 40670910, 2025). "In Greece, before the COVID-19 pandemic (2016–2018), between 3060 children tested, 5.1% of them were found with subclinical hyperparathyroidism (PTH > 45 pg/mL), with 40% of them being vitamin D deficient." (PMID 40709988, 2025). "Hyperparathyroidism (HPT) is a group of endocrine disorders caused by increased active or passive secretion of parathyroid hormone (PTH) from the parathyroid glands." (PMID 41144478, 2025). "For pancreatitis linked to hyperparathyroidism, surgery is the preferred approach, as it normalizes calcium and PTH levels, alleviating pancreatitis." (PMID 41001160, 2025). "Patients were included if they had an elevated PTH level and excluded if they had a secondary cause of hyperparathyroidism or a prior diagnosis of PA." (PMID 40608198, 2025). "The elevation in phosphate levels appears to trigger PTH synthesis (a key mechanism in chronic kidney disease-associated hyperparathyroidism)." (PMID 39040613, 2024). "Over time, net bone loss results from persistently high PTH levels in hyperparathyroidism, which also accelerates bone resorption." (PMID 38591872, 2024). "An elevated level of PTH (as in hyperparathyroidism) is often associated with a higher risk of fracture, as it leads to increased bone resorption." (PMID 39592711, 2024). "Ectopic parathyroid adenomas are associated with higher serum PTH and calcium levels, larger tumors, and a higher incidence of severe hyperparathyroidism-related bone disease (osteitis fibrosa cystica)." (PMID 39845209, 2024). "Both uncontrolled hyperparathyroidism and oversuppression of PTH are associated with adverse patient outcomes." (PMID 38919277, 2024).
hyperparathyroidism (continued). "Since Vit-D stimulates P absorption by decreasing PTH levels and Vit-D deficiency leads to decreased intestinal P absorption, this results in hyperparathyroidism (HPT) and increased renal P excretion mediated by PTH." (PMID 38732596, 2024). "Another aspect of the diagnosis pitfalls, apart from finding normal albumin-adjusted serum calcium and ionized calcium associated with high PTH levels, is the exclusion of secondary causes of hyperparathyroidism, as mentioned." (PMID 39518465, 2024). "This work represents an advance in biomedical science because as it provides a revised UK reference interval for PTH when measured using the Abbott method and therefore improves its diagnostic accuracy for hyperparathyroidism." (PMID 37139470, 2023). "The involvement of high PTH levels in protein-energy loss highlighted the need of treating hyperparathyroidism early in patients awaiting kidney transplantation." (PMID 37093441, 2023). "They include hyperparathyroidism (PTH excess), hypoparathyroidism (PTH deficiency) and pseudohypoparathyroidism (PTH resistance)." (PMID 36773188, 2023). "Hyperparathyroidism is caused by various factors that stimulate the excessive secretion of the parathyroid hormone (PTH) from parathyroid cells." (PMID 38152136, 2023). "So, hyperparathyroidism, especially tertiary hyperparathyroidism seemed to be associated with higher PTH levels and to be independent from eGFR during the first year of RTx." (PMID 37636567, 2023). "We reviewed the prevalence of MDD in patients who have hyperparathyroidism (i.e. increased PTH by any cause)." (PMID 37425517, 2023). "The association between hyperparathyroidism and platelet count can be explained by the potential mechanism of myelofibrosis induced by elevated levels of PTH." (PMID 38152136, 2023). "In a population-based study of disease prevalence, 108 of 3450 (3.1%) men and women were noted to have an elevated PTH concentration with normal serum calcium, after exclusion of secondary causes of hyperparathyroidism." (PMID 36382756, 2022). "Disorders associated with high serum PTH include neonatal severe hyperparathyroidism, familial hypocalciuric hypercalcaemia and Jansen’s metaphyseal chondrodysplasia." (PMID 33990852, 2022). "Since extracellular phosphate regulation involves change in PTH concentrations, both hypo- and hyperphosphatemia can cause hyperparathyroidism." (PMID 36382756, 2022). "Parathyroid disorder can cause excessive secretion of PTH and hyperparathyroidism, which either occurs within the parathyroid gland (primary) or outside the gland (secondary), resulting in elevated serum PTH levels." (PMID 35140213, 2022). "CKD causes hyperparathyroidism, increased UA levels, and decreased vitamin D activity, while UA decreased vitamin D levels and the parathyroid hormone decreased UA excretion." (PMID 36601015, 2022). "Normocalcemic primary hyperparathyroidism (NPHPT) is characterized by elevated serum levels of parathyroid hormone (PTH) with persistently normal serum calcium concentrations after excluding secondary causes of hyperparathyroidism." (PMID 35437440, 2022). "Excessive parathyroid hormone (PTH) is mainly caused by hyperparathyroidism due to hyperphosphatemia that occurs in CDK." (PMID 36189322, 2022). "Combining these findings with the findings from the present study, adipose tissue browning caused by excess PTH in severe hyperparathyroidism can reasonably explain the reduction in serum albumin and muscle mass." (PMID 36176632, 2022). "PC is rare among all other causes of hyperparathyroidism (parathyroid adenoma, primary parathyroid hyperplasia, parathyroid cyst, and ectopic secretion of PTH)." (PMID 35846299, 2022). "Hyperparathyroidism caused by CKD forms the accumulation of PTH in the body, triggering the mobilization of calcium in bone and fibrous osteitis." (PMID 34992536, 2021).
hyperparathyroidism (continued). "In murine hyperparathyroidism, PTH caused bone loss in mice colonized with Th17 cell-inducing taxa segmented filamentous bacteria (SFB)." (PMID 33924419, 2021). "Familial hyperparathyroidism (autosomal dominant) can conversely result from gain-of-function mutations in PTH, encoded as above." (PMID 35299844, 2021). "Moderate to severe hyperparathyroidism (PTH concentrations ≥ 600 pg/mL) is especially associated with an increase in the relative risk of death." (PMID 34202416, 2021). "For a variety of pathological reasons, the parathyroid glands can secrete excessive PTH and cause hyperparathyroidism (HP), which can be classified as primary, secondary, and tertiary." (PMID 34249998, 2021). "Excessive production of parathyroid hormone causes a common metabolic bone disorder known as hyperparathyroidism that is classified into primary, secondary, or tertiary." (PMID 32695835, 2020). "Age is not a relevant contributing factor for the occurrence of complications, while anesthesia can often cause sudden elevation of PTH levels in patients suffering from hyperparathyroidism and can worsen renal functions." (PMID 33147842, 2020). "Altered PTH metabolism underlies hyperparathyroidism and hypoparathyroidism, the complications of which affect the organs involved in calcium and phosphorous metabolism (bone and kidney) and other body systems as well." (PMID 32751307, 2020). "Here, the authors show that the intestinal microbiota is required for PTH to induce bone loss and describes mechanisms for microbiota-mediated gut–bone crosstalk in mouse models of hyperparathyroidism." (PMID 31980603, 2020). "Chronic elevation of PTH levels, as in hyperparathyroidism, has been associated with insulin-resistance and diabetes." (PMID 32751307, 2020). "Hyperparathyroidism is a generalized disorder of calcium (Ca), phosphate (P), and bone metabolism caused by increased secretion of parathyroid hormone (PTH)." (PMID 31453033, 2019). "Parathyroid hormone (PTH) causes a strong decline in the BMD of cortical bone compared to that of cancellous bone in patients with hyperparathyroidism." (PMID 29795652, 2018). "Either the increase of serum PTH levels or the presence of hyperparathyroidism was independently associated with the risk of CKD, after adjustments for confounders or by using the resampling subset of comparable baseline characteristics." (PMID 28367447, 2017). "The finding that serum PTH levels and hyperparathyroidism were independent risk factors for CKD and its surrogates (eGFR and proteinuria) was novel." (PMID 28367447, 2017). "Both the log intact PTH and hyperparathyroidism remained a significant risk factor for eGFR ≤ 60 mL/min and albuminuria, after adjustment for age, gender, serum 25 (OH) vitamin D, and calcium or phosphate levels." (PMID 28367447, 2017). "This association was consistent when serum intact PTH was analyzed as continuous as well as categorical variables (as hyperparathyroidism)." (PMID 28367447, 2017). "Hyperparathyroidism is strongly associated with HF outcomes, with elevated PTH directly related to both hospitalizations and mortality." (PMID 29084522, 2017). "In conclusion, this community-based study confirmed the association of serum levels of PTH and hyperparathyroidism with the risk of CKD." (PMID 28367447, 2017). "For example, daily injections of low-dose PTH are anabolic to the skeleton, whereas continuous exposure to PTH, the likes observed in hyperparathyroidism, results in bone loss and increased porosity especially in the cortical compartment." (PMID 27444010, 2016). "Phosphate retention causes hyperparathyroidism and bone disease, and is also a potent vascular toxin in its own right, as well as through its effects on parathyroid hormone (PTH) and fibroblast growth factor 23 (FGF23)." (PMID 25543193, 2015). "Parathyroid hormone (PTH) has been associated with anemia only in dialysis patients with severe hyperparathyroidism." (PMID 25113067, 2015).